KCNMB1 (potassium calcium-activated channel subfamily M regulatory beta subunit 1)
Description:
Regulatory subunit of the calcium activated potassium KCNMA1 (maxiK) channel. Modulates the calcium sensitivity and gating kinetics of KCNMA1, thereby contributing to KCNMA1 channel diversity. Increases the apparent Ca(2+)/voltage sensitivity of the KCNMA1 channel. It also modifies KCNMA1 channel kinetics and alters its pharmacological properties. It slows down the activation and the deactivation kinetics of the channel. Acts as a negative regulator of smooth muscle contraction by enhancing the calcium sensitivity to KCNMA1. Its presence is also a requirement for internal binding of the KCNMA1 channel opener dehydrosoyasaponin I (DHS-1) triterpene glycoside and for external binding of the agonist hormone 17-beta-estradiol (E2). Increases the binding activity of charybdotoxin (CTX) toxin to KCNMA1 peptide blocker by increasing the CTX association rate and decreasing the dissociation rate.
Synonyms: BKbeta1; Hbeta1; Slo-beta; hslo-beta; K(VCA)beta; k(VCA)beta-1; slo-beta-1
Tractability: Antibody: its Gene Ontology location is reachable by antibodies, with high confidence; UniProt predicts a signal peptide or a membrane-spanning region.
Target class: Auxiliary transport protein; Calcium-activated potassium channel auxiliary subunit slowpoke-beta family
Gene: Protein-coding gene on chromosome 5 (170,374,671 to 170,389,655, reverse strand). Ensembl gene ENSG00000145936.
Subcellular location: Membrane
Pathways (Reactome):
Sensory Perception: Acetylcholine inhibits contraction of outer hair cells; Sensory processing of sound by inner hair cells of the cochlea
Hemostasis: cGMP effects
Neuronal System: Ca2+ activated K+ channels
Gene Ontology:
Molecular function: calcium-activated potassium channel activity; potassium channel regulator activity
Biological process: chemical synaptic transmission; detection of calcium ion; neuronal action potential; potassium ion transport; potassium ion transmembrane transport
Cellular component: plasma membrane; voltage-gated potassium channel complex; membrane; synapse
Genetic constraint (gnomAD): Loss-of-function variants: 22 observed, 22.86 expected, observed/expected ratio (o/e) 0.96, 90% interval 0.69 to 1.37. The upper end of that interval is the gene's LOEUF score, 1.37, which puts it in group 5 of 6, group 1 being the genes least tolerant of losing a copy. Missense variants: 243 observed, 256.55 expected, observed/expected ratio (o/e) 0.95, 90% interval 0.85 to 1.05. Synonymous variants: 114 observed, 114.04 expected, observed/expected ratio (o/e) 1, 90% interval 0.86 to 1.17.
Homologues: Orthologues: chimpanzee KCNMB1 (99% identical), macaque KCNMB1 (95% identical), pig KCNMB1 (90% identical), guinea pig KCNMB1 (89% identical), rabbit KCNMB1 (86% identical), mouse Kcnmb1 (83% identical), rat Kcnmb1 (83% identical), dog KCNMB1 (71% identical), tropical clawed frog kcnmb1 (42% identical). Paralogues in human: KCNMB2 (42% identical), KCNMB3 (32% identical), KCNMB4 (23% identical).
Diseases named in the same sentence as KCNMB1 in open-access papers:
KCNMB1 is named in the same sentence as 28 diseases in open-access papers, as found by Europe PMC text mining. Sharing a sentence is not in itself a finding about the gene and the disease. The quoted sentences say what the papers report.
Hypertension (8 papers, 2009 to 2025). The presence of chronic increased pressure in the systemic arterial system. "Most importantly, loss-of-function mutations in the KCNMB1 lead to hypertension and renal diseases in humans." (PMID 36568562, 2022). "KCNMB1 with at least one causal gene was associated with Arterial Hypertension (q = 2.745x10-2)." (PMID 39480826, 2024). "KCNMB1 was implicated in Arterial Hypertension (q = 2.103x10-2)." (PMID 39480826, 2024). "KCNMB1 with ACTA2 was associated with Arterial Hypertension (q = 1.624x10-2)." (PMID 39480826, 2024). "Previous research has linked mutations in KCNMB1 to hypertension, myocardial infarction and stroke." (PMID 24905834, 2014). "Argininosuccinic acid (2545-fold) was cleaved by argininosuccinate lyase (ASL) into arginine and fumarate—the latter suppressing hypertension via KCNMB1 downregulation—while reducing glutathione (GSH) and elevating malondialdehyde (MDA) in brain tissues." (PMID 40941158, 2025). "Take the most confident prediction as an example, target protein ‘Endothelin-1 receptor’ (EDNRA) for ‘Bosentan’, and the disease gene ‘KCNMB1’ (Kca) for ‘Hypertension, Diastolic, Resistance To’ belong to the same pathway ‘Arachidonic Acid metabolism’." (PMID 24244318, 2013). "Interestingly, four of these genes (KCNMB1, NEDD4L, ADD1 and NPR3) have been implied in genetic susceptibility for hypertension, while two genes have been associated with genetic susceptibility for stroke (PDE4D) or myocardial infarction (ADD1)." (PMID 19750006, 2009).
cardiac arrhythmia (2 papers, 2018 to 2026). Any disturbances of the normal rhythmic beating of the heart or MYOCARDIAL CONTRACTION. "We also identified five potentially pathologic variants in genes associated with cardiac arrhythmia, including KCNMB1, KCNIP1, DPP6, JUP, F2, and TUBA3D that were identified in SUDEP patients but not present in our living epilepsy cases." (PMID 29619247, 2018).
epilepsy (2 papers, 2018 to 2024). A brain disorder characterized by episodes of abnormally increased neuronal discharge resulting in transient episodes of sensory or motor neurological dysfunction, or psychic dysfunction. "Recent studies indicated the potential of miRNAs including miR223 as potential therapeutic targets for various diseases, such as K+-channel-related cardiovascular disorders (voltage-gated K+ channel, KV4.2/KCND2) and epilepsy (voltage-gated K+ channels, KV2.1/KCNMB1 and KV7.2/KCNQ2)." (PMID 38892210, 2024).
idiopathic pulmonary fibrosis (2 papers, 2021 to 2022). Idiopathic pulmonary fibrosis (IPF) is a nonneoplastic pulmonary disease that is characterized by the formation of scar tissue within the lungs in the absence of any known cause. "Fibroblasts from patients with idiopathic pulmonary fibrosis (IPF) exhibit increased expression of KCNMB1, which codes for a β-subunit of BK." (PMID 35053420, 2022). "Finally, in idiopathic pulmonary fibrosis (IPF), increased KCNMB1 expression correlated with the differentiation of fibroblasts into myofibroblasts, leading to exacerbation of the disease." (PMID 34827626, 2021).
asthma (1 paper, 2019). "SNPs in the gene encoding the auxiliary β1 subunit, KCNMB1, are associated with increased variability in heart rate and baroreflex function and sex-specific asthma susceptibility." (PMID 31849601, 2019).
bladder cancer (1 paper, 2025). "Through multi-omics analysis combined with experimental validation, this study revealed the expression profile of KCNMB1 in bladder cancer tissues and established its association with tumor-associated immune cells for the first time." (PMID 40755754, 2025). "This study is the first to report that KCNMB1 (potassium calcium-activated channel subfamily M regulatory beta subunit 1) is significantly downregulated in bladder cancer and is negatively correlated with disease risk, suggesting tumor suppressor gene characteristics." (PMID 40755754, 2025). "It should be noted that the molecular mechanisms of KCNMB1 in bladder cancer, particularly the relationship between BK channel function mediated by KCNMB1 and tumor development, require further experimental elucidation." (PMID 40755754, 2025). "Finally, intersecting these key genes with risk-consistent genes yielded eight immune-related genes that were negatively associated with bladder cancer risk: LIMS2, TP53INP2, IRAK3, STX2, CYP27A1, IL11RA, KCNMB1, and PDLIM7." (PMID 40755754, 2025). "Although research on KCNMB1 in tumors remains limited, the gene expression features and their links to the immune microenvironment discovered in this study provide important clues for further exploration of its potential value as a biomarker for bladder cancer." (PMID 40755754, 2025). "Differential expression analysis revealed that, compared to the normal bladder cell line SV, the expression levels of LIMS2, IL11RA, KCNMB1, and PDLIM7 were significantly downregulated in all three bladder cancer cell lines (5637, T24, and HT1376)." (PMID 40755754, 2025). "Subsequent box plot analysis further demonstrated significantly lower expression of six genes (LIMS2, IRAK3, STX2, IL11RA, KCNMB1, and PDLIM7) in bladder cancer cell lines, consistent with bioinformatics analysis." (PMID 40755754, 2025). "Furthermore, KCNMB1 expression levels were significantly negatively correlated with the infiltration of naive B cells and activated dendritic cells in tumor tissues, suggesting that this gene may participate in regulating the bladder cancer immune microenvironment." (PMID 40755754, 2025). "Through integrated multi-omics analysis and experimental validation, six genes, LIMS2, IRAK3, STX2, IL11RA, KCNMB1, and PDLIM7, were selected as potential immune-related biomarkers for bladder cancer, providing promising biomarkers and therapeutic targets for personalized treatment." (PMID 40755754, 2025). "In vitro qRT-PCR validation in bladder cancer cell lines showed downregulation of LIMS2, IRAK3, STX2, IL11RA, KCNMB1, and PDLIM7, consistent with bioinformatics findings, suggesting that these genes may serve as potential therapeutic targets." (PMID 40755754, 2025). "The consistent downregulation of these genes in bladder cancer tissues was further validated using independent public datasets, and qRT-PCR experiments confirmed the differential expression of the following six genes: LIMS2, IRAK3, STX2, IL11RA, KCNMB1, and PDLIM7." (PMID 40755754, 2025).
breast carcinoma (1 paper, 2025). "Breast cancer studies included E1 (KCNMB1), E4 (KCNN3), E9 (KCNH1, KCNK15), E15 (KCNT2), E22 (KCNK5, KCNK15), E33 (KCNQ1-OT1), E38 (KCNMA1), E48 (KCNJ9), and E63 (KCNK12)." (PMID 40867621, 2025).
congenital glaucoma (1 paper, 2024). "The gene ontologies for list 7+ linked the non-overlapping genes CDC42EP2, CLDN5, CNN1, DES, KCNMB1, and MYH11 to Congenital Glaucoma." (PMID 39480826, 2024).
distal hereditary motor neuropathy type 2 (1 paper, 2024). "KCNMB1, MYH11, PNPLA2, and TAGLN linked to Distal Hereditary Motor Neuropathy type 2." (PMID 39480826, 2024). "We propose that KCNMB1, MYH11, TAGLN, and PNPLA2 are novel genes in Distal Hereditary Motor Neuropathy type 2." (PMID 39480826, 2024).
endometrial polyp (1 paper, 2024). A benign nodular lesion protruding above the surface of the endometrium. "Relevant critical genes were downregulated in endometrial polyps, including ACTA2, KCNMB1, KCNMB2, PPP1R12B, MYL9, and ACTG2." (PMID 38473810, 2024).
glaucoma (1 paper, 2024). Increased pressure in the eyeball due to obstruction of the outflow of aqueous humor. "KCNMB1 in Schlemm’s canal cells contribute to the outflow pathway thus is a regulator of intraocular pressure and may contribute to glaucoma." (PMID 39480826, 2024).
melanoma (1 paper, 2025). A malignant, usually aggressive tumor composed of atypical, neoplastic melanocytes. "It effectively prevents calcium overload in both the endoplasmic reticulum (ER) and mitochondria, which are key triggers of the ISR.The BK channel and its regulatory subunit KCNMB1 play multiple key roles in melanoma." (PMID 41409301, 2025). "KCNMB1 may promote the progression of melanoma by synergistically regulating the autonomous function of tumor cells, tumor blood vessels, and immune microenvironment." (PMID 41409301, 2025).
multisystemic smooth muscle dysfunction syndrome (1 paper, 2024). A spectrum of conditions caused by monoallelic pathogenic variants in ACTA2. "The gene ontologies for list 5+ linked FOXF1, KCNMB1, MYH11, and PLN to Multisystemic Smooth Muscle Dysfunction Syndrome." (PMID 39480826, 2024). "We propose that FOXF1, KCNMB1, and MYH11 are novel genes in Multisystemic Smooth Muscle Dysfunction Syndrome." (PMID 39480826, 2024). "No literature was located directly linking KCNMB1 (potassium calcium-activated channel subfamily M regulatory beta subunit 1) to Multisystemic Smooth Muscle Dysfunction Syndrome." (PMID 39480826, 2024).
Obesity (1 paper, 2019). Accumulation of substantial excess body fat. "Thus, impaired expression of Kcnma1 and Kcnmb1 in the DSM contributes to obesity-induced OAB, suggesting that BK channels could be a useful treatment targets in OAB." (PMID 31480021, 2019).
tumor (4 papers, 2019 to 2025). "Furthermore, analysis of the GSE13507 dataset revealed that six genes, LIMS2, IRAK3, STX2, CYP27A1, IL11RA, and KCNMB1, had AUC values greater than 0.7, demonstrating good diagnostic potential in differentiating healthy adjacent tissues from tumor samples." (PMID 40755754, 2025). "To validate the expression levels of the eight key genes (LIMS2, TP53INP2, IRAK3, STX2, CYP27A1, IL11RA, KCNMB1, and PDLIM7) in tumor and non-tumor samples, we analyzed their expression in TCGA and GSE7476 datasets." (PMID 40755754, 2025). "Furthermore, qRT-PCR experiments showed that LIMS2, IRAK3, STX2, IL11RA, KCNMB1, and PDLM7 were significantly downregulated in the tumor group, consistent with the bioinformatic analysis results, suggesting their potential clinical value." (PMID 40755754, 2025).
KCNMB1 also shares sentences with these, for which no sentence is quoted: myocardial infarction (2 papers); Stroke (2); arrhythmogenic right ventricular dysplasia/cardiomyopathy (1); autosomal dominant cutis laxa (1); cardiovascular disorder (1); coronary arteries disease (1); gestational hypertension (1); idiopathic ventricular fibrillation (1); Naxos disease (1); Polyuria (1); primary hypertension (1); pulmonary fibrosis (1); renal diseases (1).